KRAS (KRas proto-oncogene, GTPase)
Diseases named in the same sentence as KRAS in open-access papers (continued):
Sharing a sentence is not in itself a finding about the gene and the disease.
pancreatic cancer (continued). "Lack of KRAS mutational status as predictive of survival was also reported in an earlier trial study of Gemctabine and Erlotinib therapy in patients with advanced pancreatic cancer." (PMID 23565280, 2013). "Targeting specific stromal components, for example by inhibiting fibroblast activation protein (FAP), which was previously shown to reduce stromatogenesis in KRAS driven tumors of different tissues, may also reduce the stimulatory effect of the micro-environment on pancreatic tumors." (PMID 24213498, 2012). "Likewise, miR-143, which is frequently deregulated in pancreatic cancers, has been shown to interact with KRAS and restitution of tumor suppressor miRNA may inhibit tumor growth in xenograft pancreatic cancer model using nanovector delivery of miR-143/145." (PMID 22905187, 2012). "In addition, no mutation of KRAS is found in other pancreatic tumors and cholangiocarcinoma (i.e., different from PDAC); the latter result reinforces the specificity of the ≪KRAS assay≫ for PDAC." (PMID 24212643, 2011). "Reporting KRAS mutant molecules per millilitre and adopting an assay-agnostic framework distinguishing detection from quantification may improve interpretability, support harmonisation across platforms, and facilitate cumulative learning in pancreatic cancer ctDNA research." (PMID 42073641, 2026). "ZC3HAV1, a PARP family enzyme, has been shown in pancreatic cancer to regulate cell cycle progression by modulating cyclin D1 and CDK2, and to bind KRAS, enhancing its expression and activating ERK signalling to promote proliferation and metastasis." (PMID 41596441, 2026). "In pancreatic cancer development, ectopic mutant KRASG12D expression directly induced SHH transcription, suggesting that SHH is a downstream effector of oncogenic KRAS signaling." (PMID 41550359, 2026). "This review consolidates current evidence on the diagnostic, prognostic, and therapeutic potential of exosomal miRNAs in pancreatic cancer, integrating mechanistic insights into key signaling pathways such as PTEN/PI3Kγ, KRAS/MAPK, and TGF-β." (PMID 41347080, 2025). "BI‐3406 inhibits KRAS expression regardless of the mutation type; therefore, finding an effective combination therapy could hold promise for impacting > 90% of patients with pancreatic cancer." (PMID 39400496, 2025). "mRNA biomarkers (KRAS, MBD3L2, ACRV1, DPM1) can differentiate pancreatic cancer patients from healthy individuals." (PMID 39958008, 2025). "Promising activity in KRAS‐mutant ovarian cancer (ORR 29%, PFS 7 mo); limited effect in NSCLC and pancreatic cancer; high toxicity." (PMID 40740483, 2025). "Sotorasib, a KRAS G12C inhibitor, achieved disease control rates of 88.1% in the treatment of NSCLC and 84% in the treatment of pancreatic cancer." (PMID 40221400, 2025). "Targeting mutant-KRAS, CCL2, or ENSA-K63la enhances the efficacy of ICB therapy in pancreatic tumor models." (PMID 39883522, 2025). "Considering our new finding that KRAS down-regulated SIRT3 through the guanine exchange factor RCC1 in vitro, we thus further evaluated the role of RCC1 in affecting pancreatic cancer cell proliferation and tumor growth in vivo." (PMID 41391757, 2025).
pancreatic cancer (continued). "While there have been recent breakthroughs in targeting KRAS G12C in NSCLC and KRAS G12D in pancreatic cancer, there is yet to be a KRAS G12V-specific compound, and there is an unmet clinical need for strategies to target this tumor subtype." (PMID 40131933, 2025). "To assess the effectiveness of KRAS G12V high targeted-infiltration T cells against tumors in vivo, we first established CFPAC-1 pancreatic cancer models." (PMID 41472736, 2025). "We describe two cases of ERBB2-amplified pancreatic cancer patients treated with anti-HER2 therapy and provide data on the frequency of ERBB2 amplifications and KRAS alterations identified by clinical circulating cell-free DNA testing." (PMID 38406801, 2024). "Two examples, erdafitinib (FGFR inhibitor) and sotorasib (KRAS G12C inhibitor) impaired YY1 expression in genotype-matched bladder cancer cell line RT112 and pancreatic cancer cell line MIA PaCa-2, respectively." (PMID 39604408, 2024). "Of the 795 samples of pancreatic cancer, mostly PDAC, they analyzed, including samples from five cases of ACC, 9.2% were WT for KRAS." (PMID 39410042, 2024). "Besides predicting early recurrence, the panel containing serum exosomal miR-1299, GAPDH (mRNA), circulating mutant KRAS allele fraction, and CA199 levels could effectively predict occult distant metastasis of pancreatic cancer, which was significantly better than imaging alone." (PMID 39054529, 2024). "According to some reports, MYC is required for mutant-KRAS-driven tumor initiation and progression, and MYC inhibition has been demonstrated to impair the growth of pancreatic cancer." (PMID 39457457, 2024). "The PPRHs tested in combinations targeting both MYC and KRAS were G4-C or I1-T for MYC and PPRH2 or PR for KRAS, in both PC-3 and the previously examined AsPc-1 pancreatic cancer cell lines at a dose of 25 nM per PPRH." (PMID 39457457, 2024). "As for our study, pathway analysis found known PDAC driver pathways, such as KRAS, MYC, MAPK and WNT signaling pathways, enriched in the five subtypes, which supported their tumor origin." (PMID 38827297, 2024). "Overall, our findings shed light on the distinct metabolite changes induced by both KRAS status and TRPML1 inhibition in pancreatic cancer cells, providing insights into potential therapeutic targets and biomarkers for this deadly disease." (PMID 38672219, 2024).
pancreatic cancer (continued). "A comprehensive analysis of glycan expression in 16 organoids derived from 14 pancreatic cancer patients showed that the reactivity of fucose-binding lectins (AAL, AOL) was higher in 13 KRAS mutant organoids compared to 3 wild-type organoids." (PMID 38528852, 2024). "These diverse mutations converge on specific pathways and processes, including KRAS, TGF-β, WNT, Notch signaling, chromatin remodeling and DNA repair pathways." (PMID 38827297, 2024). "Gene expression profiling of pancreatic cancer cells identifies more than 200 genes commonly regulated by STAT3 and oncogenic KRAS." (PMID 38573819, 2024). "In CRC, both KRAS-wildtype (wt) and KRAS-mutant (mt) groups with TACSTD2-high tumors experienced worse OS, while in pancreatic cancer, this was observed only in patients with KRAS-mt tumors." (PMID 38986529, 2024). "The direct binding of Dclk1 to KRAS protein is the key factor in the activation of MAPK in pancreatic cancer cells, indicating the functional interaction of G9a, DCLK1, and MAPK pathways in KRAS-driven PDAC." (PMID 39839479, 2024). "In pancreatic cancer, there are three main reasons to suggest the RAF-MEK-ERK MAPK pathway is the key KRAS downstream effector pathway facilitating tumorigenesis." (PMID 38800401, 2024). "Gemcitabine-induced ROS activates KRAS/AMPK signaling, inducing metabolic reprogramming, and enhances stem cell-like properties in pancreatic cancer." (PMID 38474405, 2024). "The cause of pancreatic cancer is still unclear, and only 5%–10% of pancreatic cancer patients can be attributed to genetic factors, although the mutation rate of KRAS reaches 95%, but a single KRAS gene mutation does not lead to the development of pancreatic cancer." (PMID 36969862, 2023). "In pancreatic cancer, p38γ binds phosphofructokinase-2/fructose-2,6-bisphosphatase 3 (PFKFB3) in KRAS-transformed cells and phosphorylates PFKFB3 at S467 in human pancreatic cancer cells and in mouse KPC tumors." (PMID 37443708, 2023). "In pancreatic cancer, HSL expression is down regulated, destruction of KRAS-HSL axis reduces lipid storage, reprogrammed tumor cell metabolism, and inhibits invasive migration of pancreatic cancer." (PMID 37305043, 2023). "Further filtering for kinases led to the discovery of the Phosphatidylinositol 4-Phosphate 5-Kinase Type-1 Alpha as a KRAS G12V selective interactor, which mediated proliferation and resistance to MEK inhibitors in pancreatic cancer cell lines." (PMID 36607281, 2023). "Studies have identified KRAS, MBD3L2, ACRV1, and DPM1 as biomarkers in salivary mRNA to detect pancreatic cancer with high specificity." (PMID 38202898, 2023). "KRB-456 inhibits KRAS G12D binding to RAF1 and KRAS signaling in cultured human pancreatic cancer cells." (PMID 38051103, 2023). "For example, inhibiting the KRAS-HSL axis lowers lipid storage in lipid droplets, reducing the invasive capacity of KRAS-mutant pancreatic cancer." (PMID 37649607, 2023). "As for pancreatic cancer, STAT3 contributes to KRAS-induced PDAC initiation and progression, and inhibition of JAK–STAT3 signaling results in the impairment of a progenitor cell phenotype and abrogation of tumor sphere formation capacity." (PMID 37743465, 2023).
pancreatic cancer (continued). "It has been shown that both KRAS and EGFR are essential mediators of pancreatic cancer development and they were shown to interact with Argonaute 2 (AGO2) to perturb its function." (PMID 37686149, 2023). "Treatment of KRAS G12D-harboring human pancreatic cancer cells with KRB-456 suppresses the cellular levels of KRAS bound to GTP and inhibits the binding of KRAS to RAF1." (PMID 38051103, 2023). "Therefore, at least in the case of pancreatic cancer where the tumors appear to be highly dependent on energy from autophagy especially when KRAS or its downstream effectors are inhibited, combination of KRB-456 with autophagy inhibitors may also prove to be efficacious." (PMID 38051103, 2023). "For instance, in the context of ovarian, lung and pancreatic cancer, the tumor suppressor DIRAS3 binds to the α5 helix region of KRAS in the same pocket as P14B." (PMID 36614192, 2023). "A KRAS peptide vaccine (NCT04117087, Phase I), and a dendritic cell-based vaccine targeting the KRAS G12C, G12D, G12R, and G12V forms (NCT03592888, Phase I) are also under development for CRC and pancreatic cancer treatment." (PMID 37376135, 2023). "Using patient-derived xenografts of KRAS- and MYC-driven pancreatic carcinoma, we show that coinhibition of topoisomerase 1 (TOP1) and bromodomain-containing protein 4 (BRD4) synergistically induces tumor regression by targeting promoter pause release." (PMID 37831776, 2023). "Another study found that the gene expression of KRAS and EGFR pathway signaling molecules changed significantly after IRE treatment on pancreatic tumors." (PMID 36081554, 2022). "As a model of human PDAC, we used the human pancreatic cancer cell line COLO357PL, which carries mutant KRAS and expresses FGFR and ALK receptors as well as the ALK ligand PTN." (PMID 35326668, 2022). "We also validated the role of ceRNA network genes such as GPRC5A, SERPINB5, KRAS, EGFR, EIF4G2, and PDCD4 in pancreatic cancer." (PMID 36358856, 2022). "The KRAS-targeted siRNA-polymeric nanoparticles for local therapy, siG12D-LODER, were designed by Silenseed Ltd. for patients with locally advanced pancreatic cancer." (PMID 35890348, 2022). "In this work, we systematically evaluated proteome remodeling driven by well-known oncogenes (c-Myc, EGFR, HER2, AKT, KRAS, BRAF, or MEK) expressed in isogenic models and relevant cancer-derived and patient-derived pancreatic cancer and osteosarcoma." (PMID 35594991, 2022). "It was found that MYEOV, GPRC5A, SERPINB5, KRAS, EGFR, and EIF4G2 were all significantly elevated in pancreatic cancer tissues, and the expression trends of GPRC5A, SERPINB5, KRAS, EGFR, and EIF4G2 in different stages were nearly identical." (PMID 36358856, 2022). "Oncogenic KRAS was also reported to downregulate hormone-sensitive lipase (HSL) for lipid droplet formation, which is critical to fuel pancreatic cancer cells during metastasis and invasion." (PMID 35681705, 2022). "In order to explore the accuracy of this conclusion and the regulatory mechanism of KRAS on ITGA2, the plasmid was transfected into the pancreatic cancer cell lines to overexpress KRASG12D." (PMID 35193647, 2022). "Analysis of pancreatic cancer cell lines demonstrated that MUC1-C is overexpressed in HPAF-II (KRAS G12D) and AsPC-1 (KRAS G12D) cells, which were derived from patients with malignant ascites." (PMID 34657147, 2022).
pancreatic cancer (continued). "By screening for common oncogenes and suppressor genes, endothelium KRAS- and MYC-positive genes were enhanced in pancreatic cancer expression." (PMID 35755820, 2022). "Oncogenic KRAS is critical for the initiation and development of PDAC; however, it alone is insufficient to drive pancreatic cancer." (PMID 35681705, 2022). "Functional contributions of this phenotype were recently further identified in KRAS mutant PDAC progression; that is, enhanced macropinocytosis of extracellular fluids serves as a rapid amino acid supply route for pancreatic cancer cells." (PMID 35154474, 2022). "Next, we examined BCL6 and KRAS-GTP protein expression in various human lung, colorectal, and pancreatic cancer cell lines and observed a positive correlation." (PMID 36377663, 2022). "Particularly, KRAS and EPHA7 are highly likely to serve as prognostic factors and therapeutic targets in the management of locally advanced pancreatic cancer." (PMID 35664782, 2022). "As a potential effector of KRAS, DCLK1 contributes functionally to the pathogenesis of pancreatic cancer, and marks quiescent pancreatic progenitor cells of pancreatic origin." (PMID 36569325, 2022). "Mechanistically, KRAS inhibits IFN gene expression via regulation of the oncogene MYC, which is consistent with previous observations in pancreatic cancer." (PMID 35857848, 2022). "Currently, the most promising pancreatic cancer vaccine is GI4000, which expresses KRAS peptides of various mutant subtypes." (PMID 36118526, 2022). "In addition, the greater increase in TRIB3 expression via gossypol treatment in BxPC-3 cells than that in MIA PaCa-2 cells may not only correlate with higher toxicity, but could also result in a better therapeutic effect against pancreatic cancer cells containing wild-type KRAS." (PMID 35283426, 2022). "SEMA3C was highly expressed in pancreatic cancers, especially in cells and patients with high KRAS G12D expression, and high SEMA3C expression was enriched in the signaling pathways upregulated by KRAS." (PMID 35785187, 2022). "Cumulatively, LINC01420 facilitates progression of pancreatic cancer via releasing MYC from inhibitory effects of miR-494-3p in cytoplasm and enhancing nuclear levels of MYC-activated KRAS." (PMID 35139853, 2022). "Both KRAS and SEMA3C high expression genotypes shortened the survival time in pancreatic cancer patients." (PMID 35785187, 2022). "We analyzed mRNA expression levels of MYEOV, GPRC5A, KRAS, EGFR, SERPINB5, EIF4G2, and PDCD4 in pancreatic cancer tissues and normal tissues adjacent to pancreatic cancer from three pancreatic cancer patients." (PMID 36358856, 2022). "Beyond immunotherapeutic approaches designed to target gene-specific alterations, such as KRAS, in PDAC cells, a wide range of molecularly targeted therapies have been developed for the treatment of pancreatic cancer." (PMID 34771675, 2021). "We next dosed several KRAS mutant cell line derived xenograft (CDX) and patient‐derived xenograft (PDX) models including NSCLC, CRC, Pancreatic cancer, ovarian cancer, and esophageal cancer with IN10018." (PMID 34151545, 2021). "Of note, obesity is known to worsen mutant KRAS-mediated pathologies, leading to PDAC with high penetrance; however, the mechanistic link between obesity and pancreatic cancer remains elusive." (PMID 33668583, 2021).